VDR (vitamin D receptor)
Diseases named in the same sentence as VDR in open-access papers (continued):
Sharing a sentence is not in itself a finding about the gene and the disease.
lung tumors (1 paper, 2024). "Polymorphisms of the VDR are largely responsible for pulmonary neoplasm onset in a presumable ethnicity-, age-, and gender-dependent manner." (PMID 38928369, 2024).
lymphoid tumor (1 paper, 2022). "Higher levels of 1,25D3-MARRS was observed in all lymphoid tumor cells insensitive to test substances compared to VDR." (PMID 35053549, 2022).
lymphopenia (1 paper, 2021). Reduction in the number of lymphocytes. "This pilot study aims to investigate the role of low vitamin D status, vasculopathy, apoptotic pathways, and VDR gene polymorphisms in the immunopathogenesis of lymphopenia among Nigerian patients infected with SARS-CoV-2." (PMID 33621190, 2021). "This study is designed to investigate the role of vitamin D status, vasculopathy, apoptotic pathways, and vitamin D receptor (VDR) gene polymorphisms in the immunopathogenesis of lymphopenia among African people infected with SARS-CoV-2." (PMID 33621190, 2021).
memory impairment (1 paper, 2022). "Eriodictyol alleviated memory impairment and AD-like pathological changes by activating the Nrf2/HO-1 signaling pathway through a mechanism mediated by VDR, which provides a new possibility for the treatment of AD." (PMID 35093024, 2022).
mental disorder (1 paper, 2022). A disease that has its basis in the disruption of mental process. "One of the most studied dietary factors in relation to mental disorders is vitamin D. Exploration of vitamin D receptor (VDR) in the central nervous system (CNS) opened new insights into the so-called “non-calcemic” functions of this secosteroid." (PMID 36368945, 2022).
mesothelioma (1 paper, 2020). A usually malignant and aggressive neoplasm of the mesothelium which is often associated with exposure to asbestos. "In addition to the previously known nuclear effects of calcitriol in the control of cell proliferation, a novel finding of this study is the demonstration of the mitochondrial activity of VDR in mesothelioma." (PMID 33133014, 2020).
myasthenia (1 paper, 2025). "One study of 151 MG patients showed an association between the risk and characteristics of myasthenia and vitamin D receptor gene polymorphism." (PMID 40217903, 2025).
mycosis fungoides (1 paper, 2016). Classical mycosis fungoides is the most common type of mycosis fungoides (MF), a form of cutaneous T-cell lymphoma, and is characterized by slow progression from patches to more infiltrated plaques and eventually to tumors. "To date, mycosis fungoides (MF) has been the least studied in relation to vitamin D. Furthermore, the vitamin D receptor (VDR) single nucleotide polymorphisms (SNPs) have not been tackled before in the context of MF, despite their incrimination in numerous diseases." (PMID 27336155, 2016).
myelodysplastic syndrome (1 paper, 2023). A clonal hematopoietic disorder characterized by dysplasia and ineffective hematopoiesis in one or more of the hematopoietic cell lines. "In this study, using chromatin immunoprecipitation (ChIP) assay and siRNA, we demonstrate that vitamin D/VDR regulates PD-L1 expression in acute myeloid leukemia (AML) and myelodysplastic syndrome (MDS) cells." (PMID 37444542, 2023). "VDR/VDRE expression in the transcripts was captured by a VDR antibody in AML and myelodysplastic syndrome (MDS)." (PMID 37444542, 2023).
myelofibrosis (1 paper, 2022). A partial or complete replacement of the bone marrow stroma by fibrous tissue. "Another study suggested that VDR signaling induces macrophage differentiation and skews myelofibrosis." (PMID 36304947, 2022).
myeloid tumor (1 paper, 2022). "In the other two K562 and KG-1 myeloid tumor cells the level of VDR was higher compared to 1,25D3-MARRS." (PMID 35053549, 2022).
myocarditis (1 paper, 2023). Myocarditis is a condition that is characterized by inflammation of the heart muscle (myocardium). "It was thus suggested that a deficiency in the VDR contributes tothe development of myocarditis." (PMID 39076268, 2023).
myositis (1 paper, 2015). "Comparing the distribution of FF, Ff, and ff genotypes of the VDR gene identified a significant difference between myositis-associated autoantibody positive patients and the control population." (PMID 25649962, 2015). "Our aim was to identify a correlation between VDR polymorphisms or haplotypes and myositis." (PMID 25649962, 2015). "We did not obtain any significant differences for VDR-FokI, BsmI, ApaI, and TaqI genotypes and allele frequencies between patients with myositis and healthy individuals." (PMID 25649962, 2015).
Nephroblastoma (1 paper, 2022). An embryonal neoplasm characterized by the presence of epithelial, mesenchymal, and blastema components. "Wilms’ tumor (nephroblastoma) was generally characterized by significant VDR expression, which was seen mainly on the epithelial cells of the tubules." (PMID 35884356, 2022). "In both nephroblastoma and intact kidneys, VDR expression is characteristic of tubular epithelial cells." (PMID 35884356, 2022). "A similar pattern of VDR expression to Wilms’ tumor has been described in healthy kidneys." (PMID 35884356, 2022). "It is also suggested that the favorable prognosis for nephroblastoma may be related to the VDR pattern characteristic of mature renal tissue and the signaling pathway that facilitates maturation." (PMID 35884356, 2022).
neurofibroma (1 paper, 2022). An intraneural or extraneural neoplasm arising from nerve tissues and neural sheaths. "A possible explanation for this observation could be that NF1 neurofibromas were linked to the reduced expression of Vitamin D Receptor (VDR)." (PMID 35054138, 2022).
neutropenia (1 paper, 2018). A decrease in the number of neutrophils found in the blood. "In the discovery cohort, 18 genetic variations in genes encoding four NRs (HNF4α, PXR, PPARs, and VDR), one transcription factor (NF-κB), and one cytokine (TNF) emerged as significant (p < 0.05) predictors of severe neutropenia over the entire course of chemotherapy." (PMID 29706892, 2018).
nutritional disorder (1 paper, 2024). Any condition related to a disturbance between proper intake and utilization of nourishment. "The results confirmed that all VDR agonists were associated with metabolism and nutritional disorders, but cholecalciferol remains the least dangerous." (PMID 39770528, 2024).
oral cavity cancer (1 paper, 2023). A primary or metastatic malignant neoplasm involving the oral cavity. "In a genetic study describing the results of two different single nucleotide VDR polymorphisms (SNPs rs2107301 and rs2238135), a statistically significantly higher frequency of the SNP rs2238135 G/C genotype occurred in the oral cavity cancer group." (PMID 37242229, 2023).
oral cavity neoplasm (1 paper, 2021). A neoplasm (disease) that involves the oral cavity. "Moreover, the VDR overexpression in the course of oral cavity neoplasms was indicated in that study." (PMID 34721756, 2021).
osteophytes (1 paper, 2006). "On the other hand, the VDR a allele carriage was associated with a tendency (OR = 0.51, 95% CI = 0.25–1.03) to lowered odds of osteophyte." (PMID 16507122, 2006). "When the genotype data were used to construct haplotypes, the VDR AaTt joint genotype appeared to pose a remarkably lower odds (OR = 0.26, 95% CI = 0.08–0.91) of osteophyte compared with the AAtt joint genotype." (PMID 16507122, 2006). "The VDR AaTt joint genotype appeared to pose a remarkably lower odds of osteophyte (OR = 0.26, 95% CI = 0.08–0.91) compared with the AAtt joint genotype." (PMID 16507122, 2006). "In the present study, women with the VDR AaTt joint genotype had the lowest odds and those with the AATT genotype the highest odds of hand osteophytes as compared with the AAtt genotype." (PMID 16507122, 2006).
osteosclerosis (1 paper, 2017). Abnormally high bone density. "Collectively, these data indicate that VDR knockdown negatively affects the capability of MCF-7 cancer cells to form tumors and induce osteosclerosis in bone following direct intra-tibial inoculation in mice." (PMID 28460457, 2017).
ovarian endometriosis (1 paper, 2021). A non-neoplastic disorder characterized by the growth of endometrial tissue in the ovaries. "We analyzed VDR and AHR expression in the stroma of the tissues, both for the three phases of the endometrium and for ovarian endometriosis." (PMID 34155552, 2021). "We found significantly higher expression of VDR and AHR in the nuclei of glandular cells derived from ovarian endometriosis compared to the three phases of the normal endometrium." (PMID 34155552, 2021). "Furthermore, our data suggest that expression of VDR and AHR is mutually exclusive in ovarian endometriosis." (PMID 34155552, 2021). "Spearman’s analysis revealed a negative correlation in the expression of VDR and AHR in the nuclei of the glandular cells from ovarian endometriosis, which led us to speculate that VDR and AHR expression is mutually exclusive in this condition." (PMID 34155552, 2021).
ovarian failure (1 paper, 2011). "These morphological changes in the glands of VDR KO mice are associated with ovarian failure and reduced serum 17β-estradiol." (PMID 21298063, 2011). "Since VDR is expressed in granulosa and corpus luteal cells, the ovarian failure we observed in mice 12 months and older may represent loss of VDR regulated gene expression within ovarian tissue." (PMID 21298063, 2011). "Histological analysis indicated that the decrease in serum 17β-estradiol in aged VDR KO mice resulted from ovarian failure, as there was little evidence of follicle formation in the ovaries of VDR KO mice from 12 months of age on." (PMID 21298063, 2011). "Thus, while ovarian failure likely contributes to the activation of apoptosis and subsequent reduction in epithelial branching in the mammary gland, it does not explain the adipose tissue atrophy in VDR KO mice." (PMID 21298063, 2011).
Ovarian Hyperandrogenism (1 paper, 2019). Increased production of androgens by the ovaries. "IR and ovarian hyperandrogenism are key features of PCOS, and thus, VDR gene variants could affect the susceptibility or the phenotype of PCOS." (PMID 31870342, 2019).
periapical granuloma (1 paper, 2021). Chronic nonsuppurative inflammation of periapical tissue resulting from irritation following pulp disease or endodontic treatment. "Nuclear receptor transcription factors (RXR and VDR), posttranscriptional gene silencing, and PPARA pathways were the most abundant pathways related to periapical granuloma." (PMID 34539639, 2021). "Nuclear receptor transcription factors RXR/VDR and RORγt (which shares sequence similarity with RXR) may be involved in periapical granuloma, supported by substantial expression of IL-17A." (PMID 34539639, 2021).
Peripheral edema (1 paper, 2022). An abnormal accumulation of interstitial fluid in the soft tissues of the limbs. "The presented study is to the best of our knowledge the first one to report the association between VDR genetic variability and peripheral edema." (PMID 35517045, 2022).
phlebitis (1 paper, 2019). Inflammation of a vein. "We found a lower expression of VDR gene in males compared with females and a higher expression of VDR gene in individuals with phlebitis." (PMID 31709782, 2019). "VDR gene expression was also significantly increased in individuals with phlebitis (P = .04)." (PMID 31709782, 2019). "VDR gene expression was significantly higher in subjects with phlebitis." (PMID 31709782, 2019).
polycystic kidney disease (1 paper, 2021). A usually autosomal dominant and less frequently autosomal recessive genetic disorder characterized by the presence of numerous cysts in the kidneys leading to end-stage renal failure. "The aim of this study was to test the hypothesis that the vitamin D receptor agonist, paricalcitol (PC), either alone or with enalapril (E) (an angiotensin-converting enzyme inhibitor), reduces the progression of polycystic kidney disease." (PMID 34821697, 2021).
pregnancy disorder (1 paper, 2017). A disorder that is related to pregnancy. "The aim of this review was to summarize the existing knowledge about the role of VDR expression, function and polymorphisms in common pregnancy disorders." (PMID 29113124, 2017). "We discuss the existing literature regarding common VDR polymorphisms in these pregnancy disorders." (PMID 29113124, 2017).
pressure ulcers (1 paper, 2020). "miR-885-3p normally increases VDR activity and its downstream immune activity, and a loss of miR-885-3p binding to VDR significantly increases the risk of pressure ulcer formation in a hospital setting." (PMID 33374656, 2020). "How miR-885-3p and the VDR may interact to modulate the immune response in pressure ulcer development and wound healing is still under investigation; however, it could potentially involve modulation of the NFκB signaling pathway." (PMID 33374656, 2020).
Proteinuria (1 paper, 2025). Increased levels of protein in the urine. "Proteinuria and CKD progression: Low circulating Vitamin D might trigger the onset and progression of both kidney disease and albuminuria, while VDR activation can prevent the progression of kidney disease." (PMID 41373702, 2025).
psoriatic arthritis (1 paper, 2020). Joint inflammation associated with psoriasis. "In conclusion, VDR polymorphisms were associated with psoriatic arthritis: ApaI (7975232) polymorphism was a protective factor for disease and FokI (rs2228570) polymorphism was associated with better clinical disease activity." (PMID 33376592, 2020).
psychotic disorder (1 paper, 2018). An abnormal condition of the mind that involves a loss of contact with reality. "Therefore, we investigated the relationship between vitamin D levels and brain phenotypes in psychotic disorders, and assessed possible interactions with genetic variants in vitamin D receptor (VDR) and other genetic variants that play a role in vitamin D levels in the body." (PMID 30142216, 2018).
relapsing-remitting MS (1 paper, 2017). "In this case-control study, the expression of genes encodingvitamin D receptor (VDR) and CYP24A1 in relapsing-remitting MS (RR-MS) patientswas compared with normal individuals in the Iranian population." (PMID 28836398, 2017).
rheumatic diseases (1 paper, 2020). "In understanding the VDR gene polymorphism as a significant risk factor for rheumatic diseases, several facts need to be considered." (PMID 32550812, 2020). "The association of over 63 polymorphisms on the VDR gene and disease development in rheumatic diseases have been examined." (PMID 32550812, 2020). "Low vitamin D concentrations may, among other factors, be associated with VDR polymorphisms, introducing the potential immunosuppressive role of vitamin D in rheumatic diseases." (PMID 32550812, 2020).
scleroderma (1 paper, 2023). Scleroderma is a rare autoimmune connective tissue disorder characterized by abnormal hardening of the skin and, sometimes, other organs. "Thus, combined approaches that target both the SNAI2 and the VDR signaling systems may be more effective in treating high grade malignant cancers and possibly skin disorders involving fibrosis such as scleroderma." (PMID 37228489, 2023).
skin aging (1 paper, 2023). The gradual irreversible changes in structure of skin that occur as a result of the passage of time.. "They interact with a variety of nuclear receptors, including the vitamin D receptor, aryl hydrocarbon receptor, liver X receptors, and the retinoic acid-related orphan receptors α and γ, through which skin aging can be prevented, mitigated, or treated." (PMID 37513428, 2023).
Skin ulcer (1 paper, 2019). A discontinuity of the skin exhibiting complete loss of the epidermis and often portions of the dermis and even subcutaneous fat. "Compared with the control group, mice in the VDR−/− group displayed symptoms of loose hair, skin ulcers and erosion, urinary systemic infections, and progressive body weight loss (p < 0.05)." (PMID 31823770, 2019).
spinal diseases (1 paper, 2017). "In the 8 enrolled studies, the results of 4 articles indicate that allele F and FF genotype of VDR FokI increased the risk of spinal diseases." (PMID 29069836, 2017). "Various studies have shown that FokI polymorphism is the only one that results in different structure of VDR protein and it is associated with increased risk of spinal diseases." (PMID 29069836, 2017). "The pooled odds ratios (ORs) and 95% confidence intervals (CI) are calculated to evaluate the association between VDR gene polymorphism and spinal diseases." (PMID 29069836, 2017). "Vitamin D receptor (VDR) FokI polymorphism has been reported to influence the risk of spinal diseases." (PMID 29069836, 2017). "However, in recessive model (FF vs. Ff + ff), there is a significant association between VDR polymorphism and spinal diseases (OR = 1.209, 95% CI, 1.017–1.436)." (PMID 29069836, 2017). "First of all, this paper is focused on VDR FokI polymorphism and the risk of spinal diseases." (PMID 29069836, 2017). "Therefore, we performed this analysis to reveal the accurate relationship between VDR FokI polymorphism and spinal diseases." (PMID 29069836, 2017). "However, other investigations suggest that the FokI polymorphism of VDR is unrelated with the pathogenesis of spinal diseases." (PMID 29069836, 2017). "Therefore, VDR FokI polymorphism is related with spinal diseases." (PMID 29069836, 2017). "A large number of studies indicated that VDR gene plays crucial roles in the etiology of spinal diseases." (PMID 29069836, 2017). "However, in the genotype analysis of VDR FokI including dominant and (FF + Ff vs. ff), heterozygote comparison (Ff vs. ff) and homozygote comparison (FF vs. ff), any kind of genotype do not increase the risk of spinal diseases and no statistical difference exists in any estimates (p > 0.05)." (PMID 29069836, 2017).
squamous cell carcinoma of the anus (1 paper, 2016). "AOM treatment of VDR null mice also caused squamous cell carcinoma of the anus." (PMID 27768599, 2016).
thymoma (1 paper, 2021). A neoplasm arising from the epithelial cells of the thymus. "Haplotypes of the VDR gene between adult non-thymoma AChRAb negative MG and the control group." (PMID 33633666, 2021).
tonsillitis (1 paper, 2012). Inflammation of the tonsillar tissue. "In this study, our aim was to determine the potential role of vitamin D in recurrent tonsillitis by measuring serum 25-OH vitamin D levels and determining the vitamin D receptor polymorphism among children with recurrent tonsillitis." (PMID 22682426, 2012).
Turner syndrome (1 paper, 2023). Turner syndrome is a chromosomal disorder associated with the complete or partial absence of an X chromosome. "FokI polymorphism is associated with an increased risk of OP in Asian women and the TT FokI genotype correlates with high VDR expression in patients with Turner syndrome, supporting the hypothesis that VDR gene variants could modulate its expression pattern." (PMID 36980815, 2023).
uterine corpus endometrial carcinoma (1 paper, 2024). A endometrial carcinoma (disease) that involves the body of uterus. "The highest alteration frequency (>6%), including VDR mutation and amplification, occurred in uterine corpus endometrial carcinoma." (PMID 38639057, 2024).
uterine prolapse (1 paper, 2023). Downward displacement of the UTERUS. "This study aims to analyze the effect of Vitamin D analog supplementation on levator ani muscle strength and plasma VDR expression in uterine prolapse patients." (PMID 36869168, 2023).